PIK3CA (phosphatidylinositol-4,5-bisphosphate 3-kinase catalytic subunit alpha)
Diseases named in the same sentence as PIK3CA in open-access papers (continued):
Sharing a sentence is not in itself a finding about the gene and the disease.
endometrial cancer (continued). "PIK3CA mutations in codon 661 were reported to be present in colon cancer, whereas those in codon 901 were reported to be present in colon, breast, and endometrial cancers." (PMID 32365913, 2020). "This point is noteworthy since a previous report with copanlisib demonstrated a complete clinical responses in an endometrial cancer patient harbroing PIK3CA mutations in combination with PTEN loss." (PMID 31934607, 2020). "NRG Oncology conducted a phase II trial to assess the antitumor activity and tolerability of copanlisib, a selective inhibitor of PIK3CA, in persistent or recurrent endometrial carcinoma harboring hotspot PIK3CA mutations." (PMID 31934607, 2020). "PTEN mutations are also frequently observed and they are present in up to 50% of endometrial cancers, followed by mutations of PIK3CA (30%) and K-Ras (20%)." (PMID 30935077, 2019). "In contrast, it has been reported that coexistence of PIK3CA/PTEN mutations at high frequency (26%) in endometrial carcinoma." (PMID 31289610, 2019). "Pik3ca mutations were found in 24–36% of endometrial cancer patients, which are associated with poor prognoses such as vascular invasion." (PMID 29346447, 2018). "PIK3CA mutations occur early in endometrial cancer progression and are of high clonality from primary lesions to metastasis." (PMID 30544563, 2018). "Different from cervical cancer, TCGA database indicated that the PIK3CA H1047 mutation was more common than that of E542 and E545 mutations in breast and endometrial carcinoma." (PMID 30547809, 2018). "Among these, 12 were endometrial cancer patients and only 2 had a SD (PIK3CA mutant and/or PTEN loss)." (PMID 28008141, 2017). "Considering the high prevalence of PIK3CA mutations in endometrial cancer, and the unresolved impact in clinical and metastatic settings, we focused our study on mutations of PIK3CA5." (PMID 28860563, 2017). "Next, we wanted to assess the degree of concordance of PIK3CA hotspot mutations in a set of 32 matched pairs of primary endometrial cancers and metastases." (PMID 28860563, 2017). "An intermediate group with prevalent mutations on both pathways would include endometrial carcinoma (PIK3CA 57%, KRAS 21%), colorectal adenocarcinoma (PIK3CA 31%, KRAS 51%), or gastric adenocarcinoma (PIK3CA 24%, KRAS 16%)." (PMID 28532501, 2017). "In endometrial cancer, several hot spot mutations are found within these two exons, but they still represent only around half of the PIK3CA mutations reported." (PMID 25415225, 2015). "Her endometrial cancer had somatic cancer mutations in PIK3CA, which is frequently reported in endometrial cancer." (PMID 25588929, 2015). "An example is the finding that PIK3CA exon 20 mutations only rarely occur in cervical cancer, whereas they are a frequent finding in endometrial cancers." (PMID 24671188, 2014). "PIK3CA mutations were detected twice as frequently as predicted in cervical cancer (N = 23 predicted and N = 51 detected) and in endometrial cancer (N = 32 predicted and N = 71 detected)." (PMID 24671188, 2014). "In patients of primary endometrial carcinoma, mutation occur in PIK3CA pathway occur in 172(16.2%) tumor, mostly they were high grade tumor." (PMID 23768168, 2013). "We confirmed that all 13 endometrial cancer cell lines possess one or more alterations (mutations and/or copy number alterations) in the PIK3CA, PTEN, and K-Ras genes." (PMID 22662154, 2012). "Since finalizing these analyses, it has been reported that mutations in exons 1–7 of PIK3CA are prevalent in endometrial cancer, and comprise 50% of all mutations identified." (PMID 22383975, 2012). "We previously reported that PIK3CA mutations frequently coexist with K-Ras muations in endometrial cancer." (PMID 22662154, 2012). "Our results emphasize the potential for targeting FGFR2, KRAS and PIK3CA mutations in endometrial cancer for development of novel therapeutic strategies." (PMID 23300780, 2012).
endometrial cancer (continued). "Mutations of K-Ras (10–20%), PTEN (34–56%), and PIK3CA (25–36%) are frequently observed in endometrial cancer." (PMID 22662154, 2012). "We have validated this frequency of point mutations in PIK3CA (exon 9 and 20) in 14.6% in a cohort of 264 endometrial cancer patients." (PMID 23300780, 2012). "This is consistent with the reported mutational frequency of PIK3CA in endometrial carcinoma in the COSMIC database for PIK3CA mutations tested for in OncoMap." (PMID 23300780, 2012). "There is a phase II clinical trial currently underway utilizing MK-2206 for patients with PIK3CA mutation in recurrent or advanced endometrial carcinoma." (PMID 22911820, 2012). "In accord with our findings, single-agent BEZ235 has been shown to inhibit proliferation of endometrial cancer cells harboring PIK3CA and/or PTEN mutations by other investigators." (PMID 22039466, 2011). "The frequency of mutations for PTEN, PIK3CA and K-Ras in endometrial cancer is reported as 54, 28 and 11%, respectively." (PMID 19491896, 2009). "In endometrial carcinoma, PIK3CA mutations occurred at high frequency (36%) as did the coexistence of PIK3CA/PTEN mutations (26%)." (PMID 19384426, 2007). "In the first-in-human study of copanlisib, of 48 patients with advanced solid tumors, one patient with endometrial carcinoma exhibiting both PIK3CA and PTEN mutations and complete PTEN loss achieved a CR, two metastatic breast cancer patients had a PR, and 15 patients achieved stable disease." (PMID 39538003, 2025). "Moreover, our combination therapy reversed EMT and migratory and invasive capacity in paclitaxel-resistant, PIK3CA-mutated endometrial cancer cells, particularly via the effect of alpelisib." (PMID 37835582, 2023). "Indeed, even other gynecological epithelial cancers such as endometrial cancer are associated with the presence of numerous driver gene mutations in PIK3CA, ARID1A, PTEN, KRAS, CTNB1, and FGFR." (PMID 35740550, 2022). "The co-occurrence of MET and PIK3CA or KRAS mutations might also mediate the resistance to c-MET inhibitors when targeting the MET mutation in endometrial cancer." (PMID 34439385, 2021). "Our results with copanlisib in PIK3CA mutated recurrent endometrial cancer patients are consistent with the recent literature and suggest limited activity of single agent PIK3CA inhibitors in the treatment of chemotherapy-resistant, recurrent human solid tumors." (PMID 31934607, 2020). "•Endometrial cancer commonly harbors hotspot mutations in the PIK3CA gene." (PMID 31934607, 2020). "Finally, a trial planning to use the pan-PI3K inhibitor Copanlisib (BAY 80-6946) in patients with persistent or recurrent endometrial cancer with PIK3CA hotspot mutations was suspended (NCT02728258)." (PMID 30544563, 2018). "Mutations of Pik3ca are frequently detected in endometrial cancer." (PMID 29346447, 2018). "In addition, the mTOR inhibitors everolimus and temsirolimus demonstrated antitumor activity in endometrial cancer, with greatest sensitivity in cells with PIK3CA or PTEN mutations." (PMID 29922232, 2018). "Importantly, expression levels of the tumour suppressor genes CDKN2A and PIK3CA, which are deleted or mutated in endometrial cancer, were decreased in CTCF-altered samples (p = 0.0006 and p = 0.0007, respectively)." (PMID 30513694, 2018). "PIK3CA mutations have been associated with a better prognosis in patients with breast and esophageal cancers, but with a poorer prognosis in patients with colon, rectum, and endometrial cancers." (PMID 27388016, 2016).
endometrial cancer (continued). "In addition to our previous study, PIK3CA mutations were also assessed in exons 1 and 2 that have been recently shown to be frequently mutated in endometrial cancer." (PMID 24229379, 2013). "The frequency of mutations for PIK3CA in endometrial cancer is reported to be 28%." (PMID 20396392, 2010). "In addition, PIK3CA mutation was identified in 38% endometrial cancer samples." (PMID 31905960, 2019). "Some researchers have utilized ddPCR to detect PIK3CA or KRAS mutations in ctDNA to explore the association between ctDNA and endometrial cancer." (PMID 41602395, 2026). "The PIK3CA gene encodes the catalytic subunit of PIK3, p110a, and exhibits frequent mutations across all molecular subtypes of endometrial cancers." (PMID 41602366, 2026). "In certain high-grade endometrial cancers, mutations in ARID1A, a chromatin remodeling gene, and RAS pathway genes frequently co-occur with PIK3CA mutations." (PMID 40072110, 2025). "The prevalence of mutations was found to be relatively infrequent (i.e. alteration frequency <10%) across most tumour types except endometrial cancer and melanoma, compared to known oncogenic mutations such as KRAS or PIK3CA." (PMID 39746898, 2025). "Mutations in PIK3CA are typically activating mutations, which enhance PI3K signaling and occur in about 20–30% of endometrial cancers." (PMID 40072110, 2025). "In endometrial cancer, BYL719 (alpelisib) has been studied in clinical trials, revealing moderate efficacy in cases with specific PIK3CA mutations." (PMID 40072110, 2025). "Resistance to treatment in endometrial cancer often occurs due to activation of the PI3K/AKT/mTOR pathway, especially in tumors with mutations in the PIK3CA gene or loss of PTEN function." (PMID 39925739, 2025). "Mutations in PIK3CA, which encodes a subunit of the PI3K enzyme, are also frequently found alongside CTNNB1 mutations in endometrial cancer." (PMID 40072110, 2025). "For example, in endometrial cancers, mutations in CTNNB1 frequently co-occur with mutations in PIK3CA, PTEN, and ARID1A, particularly in high-grade endometrioid carcinomas." (PMID 40072110, 2025). "The molecular characteristics of endometrial carcinomas revealed distinctive PTEN, PIK3CA, PIK3R1 and K-RAS mutation." (PMID 41233892, 2025). "The mTOR pathway also plays a role in the development of endometrial cancer with a high frequency of mutations in PTEN and/or PIK3CA." (PMID 39156285, 2024). "The PIK3CA signal transduction pathway is one of the major pathways activated in endometrial cancers." (PMID 38408048, 2024). "For example, the PIK3CA c.3140A>G (p.His1047Arg) mutation is known to activate the PI3K/AKT pathway, which is a critical driver of oncogenesis in endometrial cancer." (PMID 39296440, 2024). "In AH/EIN, the most commonly mutated genes, including PTEN, CTNNB1, ARID1A, PIK3CA, and KRAS, are also mutated in endometrial carcinoma." (PMID 38539494, 2024). "The PI3K–AKT pathway is one of the most dysregulated signaling pathways in endometrial cancer, which is caused by mutations in tumor suppressor genes, i.e., PTEN and PIK3CA." (PMID 37869088, 2023).
endometrial cancer (continued). "Of the common cancer-associated genes, several genes such as PIK3CA, KRAS, FBWX7, and PPP2R1A are frequently mutated in uterine normal endometrium, which is the origin of both endometriosis and endometrial cancer." (PMID 38067342, 2023). "The TCGA analysis of endometrial cancers has showed that many of these ancestral genes (PTEN, PIK3CA, KRAS, ARID1A, or CTNNB) are frequently mutated (26–80%) indicating that they are likely drivers of oncogenesis." (PMID 36299398, 2022). "Fibroblast Growth Factor Receptor (FGFR2) mutation was identified in approximately 10% of patients with primary endometrial cancer and more than 90% of patients with PIK3CA activation." (PMID 35409155, 2022). "The 3 tamoxifen-associated EMPs were not distinctive with respect to their spectrum of definitive endometrial cancer driver mutations, which included FGFR2, PIK3CA, and FBXW7." (PMID 35798968, 2022). "The PIK3CA gene was situated as the second more altered gene (60%), which is in accordance with described molecular genetics data in endometrial carcinomas." (PMID 36010253, 2022). "In endometrial carcinomas, the frequently altered genes were PIK3CA (51%) and PTEN (43.1%), consistent with the findings of similar studies." (PMID 35267660, 2022). "Gene mutations in PIK3CA, PIK3R1, KRAS, PTEN, and PPP2R1A commonly detected in type I endometrial cancer cause high activation of the PI3K/Akt/mTOR pathway." (PMID 34831139, 2021). "First, mutations in PIK3CA and KRAS cause the aberrant activation of downstream signaling pathways, contributing to tumorigenesis and disease progression in endometrial cancer." (PMID 34439385, 2021). "At the molecular level, type I endometrial cancer is associated with mutations in genes such as PTEN, KRAS, ARID1A, PIK3CA, and CTNNB1 and microsatellite instability (MSI)." (PMID 34565373, 2021). "These endometrial cancers showed common mutation profiles, including PTEN, CTNNB1, PIK3CA, and PIK3R1 mutations." (PMID 32652986, 2020). "•NRG-GY008 evaluated the activity of copanlisib, an inhibitor of PIK3CA, in recurrent endometrial cancer patients." (PMID 31934607, 2020). "A total of 49 FFPE and LBC specimens (n = 24) were analyzed, revealing characteristic mutations for endometrial cancer, including PTEN, CTNNB1, PIK3CA, and PIK3R1 mutations." (PMID 32652986, 2020).
endometrial cancer (continued). "The high frequency of the mutation of PIK3CA, a key gene that encodes the PI3K alpha subunit, has been described in endometrial cancer." (PMID 30935077, 2019). "Of the genes involved in this pathway examined in our study, PTEN, PIK3CA, and PIK3R1 all mutated frequently, which was similar to the TCGA study on endometrial carcinoma." (PMID 30886832, 2019). "About 80% of endometrial cancers are Type I, which has several mutations, including microsatellite instability (MSI), KRAS, PTEN, PIK3CA, and β-catenin." (PMID 29922232, 2018). "Molecular alterations of EGFR and PIK3CA, which are found in the endometrial cancer signaling network, have been reported in endometrial cancer studies." (PMID 29912931, 2018). "The frequency of PIK3CB mutation is lower compared to the PIK3CA gene, with reported frequencies of 2% (COSMIC), 10% (TCGA-UCEC, release 13) and 8% (TCGA endometrial cancer genomic data)." (PMID 30544563, 2018). "Much of the research and clinical efforts have focused on PIK3CA/p110α but are starting to include PIK3CB/p110β in light of its association with loss of PTEN, the most frequent genetic alteration in endometrial carcinomas." (PMID 30544563, 2018). "We also analyzed the mRNA levels of PIK3CB compared to PIK3CA in a cohort of endometrial cancer patients, including 18 with complex atypical hyperplasia (CAH), 174 primary tumors and 42 metastatic lesions." (PMID 28002804, 2017). "Each group only had one patient with a PR, indicating a limited activity of this AKT inhibitor administered as a single agent and independently of the PIK3CA status in endometrial cancer patients." (PMID 28008141, 2017). "Mutations in both PIK3CA and PTEN genes were most prevalent in endometrial-carcinoma samples (4/17, 24%) and triple-negative breast-cancer samples (5/27, 19%)." (PMID 29137436, 2017). "Recently, the mTOR pathway has been found to play a crucial role in the development of endometrial cancer with high frequency of mutations in PTEN and/or PIK3CA; knowledge about genetic alterations involved in this pathway offer potential treatment strategies." (PMID 27377753, 2016). "PI3K activation is influenced by multiple changes in endometrial cancer, including most frequently PTEN loss of function, PIK3CA mutations and PIK3CA amplification." (PMID 25415225, 2015). "Mutations in the catalytically active protein (PIK3CA/p100α) and the regulatory protein (p85α), which form the PI3K complex, have been reported in glioblastoma, ovarian, breast, colon, and endometrial cancers." (PMID 26404379, 2015). "Although MCF7 contains a moderately activating mutation of PIK3CA, depletion of ARID1A by siRNA considerably increased phosphorylation of AKT at Ser-473 in this cell line in endometrial carcinoma cell lines." (PMID 24979463, 2014).